RASA1 (RAS p21 protein activator 1)
Diseases named in the same sentence as RASA1 in open-access papers (continued):
Sharing a sentence is not in itself a finding about the gene and the disease.
tumor (continued). "It regulates the transcription activity of various genes including p21, and thus inhibits cell-cycle progression.On the other hand, RASA1, a RAS signaling terminator, is associated with tumor progression." (PMID 27135244, 2016). "CDKN2A, PIK3CA, RASA1 and DMD variants were exclusively linked to smoking, chewing, HPV infection and tumor stage." (PMID 26834999, 2015). "The ability of DOK2 to inhibit EGF-induced activity of wild-type RAS and the fact that DOK2 is constitutively bound to RASA1 in cells harboring EGFRL858R suggest that at least part of DOK2’s tumor suppressive function is to suppress RAS activation via RASA1." (PMID 24255704, 2013). "However, since RASA1 encodes an effector of the RAS pathway involved in carcinogenesis, its role in tumor etiopathogenesis in the patient cannot be excluded." (PMID 38874808, 2024). "However, we corroborated the tumor-suppressive roles of insertions in Adk and Zbtb20 and in Nipbl, Pdlim5, Ppp1r12a, Tnrc6b, Brd4, Cul3, Ctnna3, Elavl1, Gphn, Nfia, Ptpn12, Taok3, and Rasa1." (PMID 33435458, 2021). "Although RASA1 can mitigate Ras activity, its role in cancer has remained unclear for a long time; recent works described RASA1 inhibition by non-coding RNA in multiple aggressive tumors, supportive of a tumor-suppressive activity." (PMID 33096593, 2020). "Research in the mechanism of miR-31 found that it could target genes such as ARID1A, SATB2, ARID1A, HuR, BAP1, EZH2, and RASA1, and it could further activate oncogenes and promote tumor cell proliferation, migration and invasive capability in vitro." (PMID 28404921, 2017). "Although this suggests that RASA1 may play tumor suppressive roles in many cancer types, the functional impact of these mutations as well as the role of RASA1 in tumorigenesis has not been previously addressed in detail." (PMID 26993606, 2016). "Therefore, tumor growth in mice is inhibited by wild type RASA1, but it is enhanced by RASA1 Y472H mutant, which is consistent with their effect on soft agar colony formation in vitro." (PMID 26993606, 2016). "Interestingly, the RASA1 Y472H mutant promoted colony growth in these cells, converting RASA1 from a tumor suppressor to a putative oncogene." (PMID 26993606, 2016). "We observed a strong association between somatic variations in some key genes with one or more risk habits; for example,CDKN2A andPIK3CA with smoking;CASP8 with consuming alcohol and chewing tobacco;RASA1 with chewing and tumor stage, and HPV infection, along withDMD andPIK3CA." (PMID 26834999, 2015). "Rasa1 exerted a tumor suppressor function by removing GTP from RAS-GTP." (PMID 22073238, 2011). "This region contains the RASA1 gene which exhibits tumor suppressor activity on the RAS gene." (PMID 21339820, 2011). "Rasa1 exerts a tumor suppressor function by removing GTP from RAS-GTP." (PMID 22073238, 2011). "Among the altered genes, BNC2 is a putative tumor suppressor; RASA1 gene (Ras p21 protein activator 1) is the regulator of Ras oncogene, and mutation in RASA1 may turn on oncogenic pathways; Smad2 is a tumor suppressor; and Yap1 is an oncogenic co-activator in the Hippo pathway when overexpressed." (PMID 36865791, 2023). "The Ras p21 protein activator 1 gene (RASA1) is responsible for the RAS pathway regulation by controlling its ligation with GDP and GTP, and thus is considered a tumor-suppressor gene of the RAS/GAP group." (PMID 37368773, 2023). "RASA1 (Ras GTPase-activating protein 1) is a regulator of Ras GDP and GTP that promotes the pathological processes of vascular disease and tumor formation." (PMID 37446885, 2023). "Ras p21 protein activator 1 or Ras GTPase-activating protein (RASA1) expression is prevalent in TNBC tumors and is a tumor suppressor." (PMID 38202644, 2023). "The model showed that patients with lower tumor stage, higher RAC1 methylation levels, WT NTRK3, higher Tr cell infiltration in the TME, and RASA1 CNV survived better than other patients with opposite status." (PMID 35936718, 2022).
tumor (continued). "For instance, miR-21 directly targets tumor suppressive PTEN, SESN1, CAB39L, and RASA1 in different types of cancer to regulate different cancer cell behaviors." (PMID 31500623, 2019). "As a tumor suppressive role has predominantly been suggested for both NF1 and RASA1, we continued to investigate both their function in CRC." (PMID 30858928, 2019). "In contrast, miR-132 is highly overexpressed in tumor endothelium, where it stimulates VEGF driven Ras-Raf-Mek-Erk signaling through targeting RAS p21 protein activator (RASA1; p120 RasGAP), a negative regulator of Ras." (PMID 28474282, 2017). "By randomly assessing the potential target genes in the tumor samples, we have found that up-regulated SOX9, RASA1, CEP55 and MAP4K4, the target genes of miR-582, might play important roles in LUAD tumorigenesis." (PMID 33510968, 2021). "These cell lines stem from disparate tumor or tissue types, but they were all predicted to have very high recruitment of CRKL (more than one copy of CRKL bound to each molecule of IGF1R) coupled with moderately high recruitment of either SRC, SHC1, or RASA1." (PMID 30653502, 2019). "Whereas several publications have proposed a tumor suppressor role for RASA1 in CRC, we did not observe elevated levels of RAS and ERK activity in RASA1 knock out organoids at basal conditions." (PMID 30858928, 2019). "To determine whether RASA1 can suppress tumor growth in vivo, we injected WM983C cells harboring a vector control, RASA1 wild type, or RASA1 Y472H mutant into nude mice subcutaneously (n = 7 each)." (PMID 26993606, 2016). "Of notice, study patients demonstrating high tumor PI3K-mediated signaling activity, as all array substrates of this specific pathway (PIK3R1, CTTN1, PLCG1, PDPK1, and RASA1) were highly phosphorylated, had particularly poor metastasis-free survival after radical treatment of the pelvic cavity." (PMID 23226389, 2012). "One of the tumors with a RASA1 deletion did not have a gain in any of the activating genes in this pathway, suggesting a mechanism of H-Ras activation in this tumor." (PMID 16457699, 2005). "Our data, together with observations that ubiquitous loss of RASA1 in mice does not lead to spontaneous tumor formation, questions whether RASA1 functions as an essential tumor suppressor in the gut." (PMID 30858928, 2019).
cancer (45 papers, 2013 to 2026). A tumor composed of atypical neoplastic, often pleomorphic cells that invade other tissues. "The combined inhibition of Bcl-xL and YAP synergistically suppressed cancer stemness and in vivo metastasis in RASA1 and NF2 co-deficiency." (PMID 37730636, 2023). "Some studies have shown that mutation or loss of function of RASA1 leads to activation of the RAS-MAPK cascade in malignant tumors." (PMID 31857500, 2019). "The loss of RASA1 provided cancer cells with a survival advantage via the Ras/RAF/MEK/ERK pathway." (PMID 37730636, 2023). "RASA1 deficiency amplified the Wnt pathway via Bcl-xL, contributing to cancer stemness." (PMID 37730636, 2023). "We hypothesized that MAPK activation resulting from Rasa1 deficiency could upregulate Bcl-xL and consequently boost cancer stemness." (PMID 37730636, 2023). "To further investigate our hypothesis that the mutated RASA1 transcript is unstable and possibly degraded, we compared the mRNA expression levels of RASA1 in the three cell lines that contain the C2330T mutation to the remainder of the cancer cell lines in the Cell Line Encyclopedia." (PMID 24465899, 2014). "NF2 and RASA1 deficiency increased in vivo metastasis and in vitro tumorsphere formation by synergistically amplifying Wnt and YAP signaling in cancer stem cells (CSCs)." (PMID 37730636, 2023). "Increasing evidence has pinpointed that RASA1 is involved in numerous cancer-related physiological processes such as angiogenesis, cell proliferation, and apoptosis." (PMID 37390335, 2023). "Another study showed that exogenous miR-335 expression repressed expression of RASA1, which has been reported to play role in cancer cell invasion." (PMID 29075357, 2017). "Additional study is needed to reveal a possible broader role for RASA1 inactivation in other cancer types." (PMID 26993606, 2016). "These three cell lines express significantly less RASA1 than the majority of other cancer cell lines in the database." (PMID 24465899, 2014). "Given that loss-of-function in NF1 and RASA1 may lead to increased Ras activity and downstream MEK signaling, we tested small molecule targeting of the RAS-MAPK pathway in sinonasal malignancies." (PMID 40475474, 2025). "SOS1, RASA1, and NF1 mutations were also significantly more often observed in CDX2-suppressed cancers (10.8%, 9.2% and 13.8%, respectively) than in non CDX2-suppressed cancers (1.8%, 1.8%, and 0.9%, Fisher’s exact test p = 0.003, 0.009, and 0.0001, respectively)." (PMID 39452477, 2024). "Kyoto Encyclopedia of Genes and Genomes (KEGG) pathway enrichment analysis of differentially expressed genes with > threefold changes in Rasa1- and Nf2- KO tumorspheres compared to that in controls revealed the most pronounced changes in Pathways in cancer (KEGG 05200)." (PMID 37730636, 2023). "The dysregulation of RASA1 plays an important role in the progression of malignant tumors, so it may become a predictor for prognosis and therapeutic target." (PMID 31857500, 2019). "This further strengthens our hypothesis that NF2 and RASA1 deficiency induces changes in cancer stemness, as CSCs are capable of mimicking and modifying normal developmental processes to support cancer cell survival and proliferation." (PMID 37730636, 2023). "The results revealed that SOX9, RASA1, CEP55, and MAP4K4 were significantly higher expressed in LUAD tissues than those in adjacent cancer tissues." (PMID 33510968, 2021). "RASA1 and FIH-1 play important roles in many cellular and biological processes, including anti-cancer drugs resistance and proliferation regulation." (PMID 31762810, 2019).
cancer (continued). "In line with previous observations, genes involved in cancer development were represented on Bs of four studied species: red fox (KIT), Chinese raccoon dog (ENPP1, GNAS, HMGCR, KDR, RET), brocket deer (BCL6, RASA1, RET), and Korean field mouse (JAK3)." (PMID 30103445, 2018). "It has been shown that RASA1 acts as a suppressor of the activity of the RAS-MAPK signaling pathway, which is crucial in the regulation of cell proliferation and apoptosis in various types of cancer." (PMID 24223656, 2013).
vascular disorder (3 papers, 2015 to 2023). A general term used to describe any disease affecting blood vessels]. "Loss of EPHB4 or RASA1 function in EC results in dysregulated Ras-MAPK signaling that drives the development of vascular abnormalities in CM–AVM and other vascular disorders." (PMID 37259315, 2023). "Use of NGS-based gene panels including not only ENG, ACVRL1 and MADH4 but also RASA1 and EPHB4 genes, which are associated with the HHT-like syndrome accelerates the diagnosis of these hereditary vascular disorders." (PMID 33807613, 2021). "In this study, we tested for mutations in two genes, RASA1 and GDF2, which were recently reported to be involved in vascular disorders." (PMID 27081547, 2015). "Alternatively, because loss of RASA1 or EPHB4 function is initially expected to be localized to individual EC in human vascular disorders, it is possible that adjacent RASA1- or EPHB4-sufficient EC can rescue RASA1- or EPHB4- null EC from apoptosis through provision of collagen IV in trans." (PMID 37259315, 2023).
adenocarcinoma (2 papers, 2023 to 2025). A common cancer characterized by the presence of malignant glandular cells.
RASA1 also shares sentences with these, for which no sentence is quoted: Noonan syndrome (5 papers); genetic disorder (4); gastric cancer (3); cardiovascular diseases (2); cerebral cavernous malformation (2); colorectal tumor (2); cutaneous melanoma (2); fibrosis (2); head and neck carcinoma (2); infection (2); Obesity (2); pulmonary arterial hypertension (2); acute myocardial infarction (1); AIDS (1); aneurysm (1); arrhythmogenic right ventricular cardiomyopathy (1); autosomal dominant disease (1); bladder tumor (1); brain disease (1); breast tumor (1); cardiofaciocutaneous syndrome (1); colorectal adenocarcinoma (1); Coma (1); dysplastic nevi (1); ectodermal dysplasia (1); endometrial cancer (1); fetal hydrops (1); glioma (1); heroin addicts (1); hydrops (1).
A further 38 diseases each share a sentence with RASA1 in 1 paper.